LETM1 (leucine zipper and EF-hand containing transmembrane protein 1)
Diseases named in the same sentence as LETM1 in open-access papers (continued):
Sharing a sentence is not in itself a finding about the gene and the disease.
gastric cancer (2 papers, 2021). A primary or metastatic malignant neoplasm involving the stomach. "It has been reported that high expression of LETM1 reduced the survival rate of gastric cancer patients." (PMID 34605738, 2021). "In the previous studies, it is interesting to note that the analysis of gastric cancer tissue sections and gastric cancer cells revealed that knockdown of LETM1 greatly inhibited the cancer cell growth, migration and invasion and affected cell distribution." (PMID 34605738, 2021).
hepatocellular carcinoma (2 papers, 2020 to 2021). A malignant tumor that arises from hepatocytes. "Relationship between LETM1 expression and clinicopathologic features in patients with hepatocellular carcinoma." (PMID 33552978, 2020). "In contrast with studies that associate LETM1-overexpression with promotion of tumorigenesis, other studies demonstrated that LETM1 over-expression impaired mitochondrial biogenesis, compromised ATP production, and elicited necrotic cancer cell death in lung and hepatocellular carcinoma." (PMID 33815143, 2021). "However, the biological role and molecular mechanism of LETM1 in the progression of hepatocellular carcinoma (HCC) remain largely unknown." (PMID 33552978, 2020). "Based on the findings to date, we hypothesized that LETM1 regulates autophagy and apoptosis through activation of AMPK-mediated Beclin-1/Bcl-2 complex dissociation in hepatocellular carcinoma." (PMID 33552978, 2020).
Intellectual disability (2 papers, 2014 to 2022). "Furthermore, considering the high energy demands of the brain, LETM1-dependent mitochondrial dysfunction could impact upon other aspects of optimal neuronal function that might be relevant to intellectual disability herein." (PMID 24626991, 2014).
neuroblastoma (2 papers, 2014 to 2017). Neuroblastoma (NB) is the most common solid, extracranial childhood tumor. "Using the mouse neuroblastoma cell line Neuro2A as a model system, we investigated whether siRNA-mediated reduction of Letm1 alone could recapitulate some of the novel mitochondrial phenotypes we have described here in LETM1-haploinsufficient WHS-patient LCLs." (PMID 24626991, 2014). "We further confirmed the interaction of endogenous PINK1 with LETM1 from human post-mortem brain and human SH-SY5Y neuroblastoma cells." (PMID 29123128, 2017).
Obesity (2 papers, 2021 to 2022). Accumulation of substantial excess body fat. "Consequently, changes in LETM1 expression and function are associated with pathophysiologies, such as insulin resistance in obesity, tumorigenesis, and seizures." (PMID 33815143, 2021). "We found that the regulatory effect of TRPV1 on LETM1 was critical to restrain obesity and related hypertension, and the knockout of TRPV1 further exacerbated obesity in UCP1 knockout mice, resulting in more severe hypertension." (PMID 35043013, 2022). "The present study revealed a previously unrecognized role of LETM1 in obesity-related hypertension by acting as a mitochondrial Ca2+ modulator in BAT." (PMID 35043013, 2022). "This study provides in vivo evidence for the critical role of BAT mitochondrial Ca2+ homeostasis in obesity-associated hypertension and indicates that the TRPV1/UCP1/LETM1 complex may be an alternative intervention target." (PMID 35043013, 2022). "It is suggested that, in obesity, LETM1 and CTMP may counter-regulate each other’s function since LETM1 expression is inversely correlated with the expression of CTMP and positively correlated with Akt phosphorylation and activity." (PMID 33815143, 2021). "Thus, by acting as a critical regulator of mitochondrial Ca2+ homeostasis, LETM1 might also be involved in the process of adipose tissue dysfunction that results in obesity-related hypertension." (PMID 35043013, 2022). "LETM1 impairs insulin signaling and the PI3K/PKB pathway in the adipose tissue of obese mice, and its expression is reduced in obesity." (PMID 35043013, 2022).
temporal lobe epilepsy (2 papers, 2014 to 2022). A localization-related (focal) form of epilepsy characterized by recurrent seizures that arise from foci within the temporal lobe, most commonly from its mesial aspect. "These authors also reported lower LETM1 expression in the temporal neocortex of individuals with temporal lobe epilepsy compared with normal individuals." (PMID 24626991, 2014). "The mechanism linking LETM1 and seizures in WHS or temporal lobe epilepsy is, however, still poorly explored." (PMID 35697381, 2022).
3-methylglutaconic aciduria (1 paper, 2022). A group of five inherited disorders caused by mutations in the AUH, DNAJC19, OPA3, and TAZ genes. "Akin to defects in OPA3, 3-methylglutaconic aciduria was a frequent finding in the subjects with bi-allelic LETM1 variants." (PMID 36055214, 2022).
amyotrophic lateral sclerosis (1 paper, 2021). Amyotrophic lateral sclerosis (ALS) is a neurodegenerative disease characterized by progressive muscular paralysis reflecting degeneration of motor neurons in the primary motor cortex, corticospinal tracts, brainstem and spinal cord. "In patients with amyotrophic lateral sclerosis (ALS), LETM1 expression is implicated in mitochondrial dysfunction." (PMID 33815143, 2021).
anaplastic thyroid carcinomas (1 paper, 2016). "Reinforcing our observations regarding the relationship of LETM1 with cellular growth signaling, LETM1 silencing resulted in decreased protein levels of PDGFB and mRNA expression of PDGFB, PDGFBR and THBS4 in BCPAP cells and 8505C cells (human anaplastic thyroid cancer cell line)." (PMID 27556512, 2016).
breast invasive cancer (1 paper, 2021). "MCU, its dominant-negative form MCUb, LETM1, and VDAC, were found to be upregulated in breast invasive cancer." (PMID 33614647, 2021).
cardiac hypertrophy (1 paper, 2025). "Expression analyses revealed that Letm1 transcript levels were significantly downregulated in human cardiac samples from patients with heart failure (HF) due to cardiac hypertrophy (HCM) but significantly upregulated in ischemic cardiomyopathy (ICM)." (PMID 40849623, 2025). "Letm1 expression was assessed in human and murine models of heart failure due to ischemic cardiomyopathy (ICM) and cardiac hypertrophy." (PMID 40849623, 2025). "Similar regulation was observed in murine models- Letm1 levels increased after cardiac ischemia induced by left anterior descending (LAD) artery ligation but decreased (non-significant) after cardiac hypertrophy due to pressure overload induced by O-ring aortic banding (ORAB)." (PMID 40849623, 2025).
cardiac ischemia (1 paper, 2025). "To evaluate the clinical relevance in cardiac pathophysiology, we determined the expression of Letm1 in the hearts of human patients and mouse models of cardiac ischemia and heart failure." (PMID 40849623, 2025).
cardiomyopathies (1 paper, 2025). "Although genetic alterations in Letm1 are linked to cardiomyopathies, its specific contributions to cardiac pathophysiology, particularly in the context of ischemic heart disease, remain poorly defined." (PMID 40849623, 2025).
cataract (1 paper, 2022). Partial or complete opacity of the crystalline lens of one or both eyes that decreases visual acuity and eventually results in blindness. "Bilateral cataracts and facial dysmorphism observed in the present LETM1 cohort have also been reported in individuals with defective OPA3 and MSTO1, respectively." (PMID 36055214, 2022).
cervical cancer (1 paper, 2022). A primary or metastatic malignant neoplasm involving the cervix. "LETM1 is a target of miR-613 in suppressing cervical cancer progression." (PMID 35832191, 2022). "In addition, we examined the mRNA expression of RNF4, OCIAD1, TMED5, DHX15, MED28, and LETM1 in TMEM33 knockdown cervical cancer cells." (PMID 35832191, 2022).
colon cancer (1 paper, 2014). "Western blot data from liver and colon cancer tissue also demonstrated similar results, showing that high LETM1 protein expression raises the exciting possibility of using LETM1 as a tumor marker." (PMID 24689060, 2014).
colorectal tumours (1 paper, 2021). "Thus, LETM1 may promote the progression of colorectal tumours." (PMID 33314691, 2021).
Epileptic encephalopathy (1 paper, 2022). A condition in which epileptiform abnormalities are believed to contribute to the progressive disturbance in cerebral function. "The affected individual from family 9 was homozygous for the LETM1 variant c.1139G>C (p.Arg380Pro) and presented respiratory insufficiency, epileptic encephalopathy, neuromuscular disorder, and rapid disease progression." (PMID 36055214, 2022).
head and neck cancer (1 paper, 2016). A primary or metastatic malignant neoplasm affecting the head and neck. "Supporting the proto-oncogenic properties of LETM1, human multiple tissues arrays have also demonstrated increased expression of LETM1 in various cancers, including breast, head and neck cancers." (PMID 27556512, 2016).
head and neck squamous cell carcinoma (1 paper, 2014). A squamous cell carcinoma that arises from any of the following anatomic sites: lip and oral cavity, nasal cavity, paranasal sinuses, pharynx, larynx, and salivary glands. "This study explored the clinicopathological significance of LETM1 expression as a prognostic determinant in head and neck squamous cell carcinoma (HNSCC)." (PMID 24689060, 2014).
heart failure (1 paper, 2025). Inability of the heart to pump blood at an adequate rate to meet tissue metabolic requirements. "Furthermore, while our study identifies key molecular and functional consequences of Letm1 dysregulation, the long-term in vivo impact on cardiac structure and function, particularly in the context of disease models such as ischemia or heart failure, remains to be fully elucidated." (PMID 40849623, 2025).
Hypertension (1 paper, 2022). The presence of chronic increased pressure in the systemic arterial system. "However, whether there exists any relationship between TRPV1 and LETM1 that regulates both cellular Ca2+ homeostasis in adipose tissue and how they cooperate in the development of hypertension are still unclear." (PMID 35043013, 2022). "However, in UCP1 knockout mice, when the inhibitory effect of TRPV1 on LETM1 disappeared, the knockout of TRPV1 reversely aggravated mitochondrial calcium disorder and subsequent ROS production in BAT, which led to the development of hypertension." (PMID 35043013, 2022).
Insulin resistance (1 paper, 2021). Increased resistance towards insulin, that is, diminished effectiveness of insulin in reducing blood glucose levels. "The association between LETM1 methylation and fasting insulin levels suggests that it can serve as an epigenetic marker to indicate future development of insulin resistance and Type II diabetes in obese individuals." (PMID 33815143, 2021). "Thus, in liver cells from obese and high fat diet-fed mice, a decrease in LETM1 expression was associated with a reciprocal increase in CTMP expression and a decrease in Akt activity, suppression of insulin signaling and cellular glucose uptake, and development of insulin resistance." (PMID 33815143, 2021).
ischemia (1 paper, 2025). A hypoperfusion of the BLOOD through an organ or tissue caused by a PATHOLOGIC CONSTRICTION or obstruction of its BLOOD VESSELS, or an absence of BLOOD CIRCULATION. "Moreover, in vivo models are needed to validate the translational relevance of Letm1-targeted therapies in improving cardiac outcomes post-ischemia." (PMID 40849623, 2025).
ischemic cardiomyopathy (1 paper, 2025). Ischemic cardiomyopathy is a cardiomyopathy in which a weakness in the muscle of the heart due to inadequate oxygen delivery to the myocardium with coronary artery disease being the most common cause. "Our findings demonstrate for the first time that Letm1 is significantly upregulated in ischemic cardiomyopathy in both human and mouse models." (PMID 40849623, 2025). "In this study, we uncovered a novel role of Letm1 in ischemic cardiomyopathy, demonstrating that it is upregulated in both human and murine models of ischemic heart disease." (PMID 40849623, 2025). "This study indicates that Letm1 upregulation drives mitochondrial dysfunction, electrophysiology alterations, and activation of autophagy and apoptosis, culminating in cardiomyocyte injury in ischemic cardiomyopathy." (PMID 40849623, 2025). "Interestingly, although both ischemic cardiomyopathy (ICM) and hypertrophic heart disease (HCM) involve mitochondrial dysfunction and cardiomyocyte stress-induced apoptosis, our findings reveal that Letm1 expression is selectively upregulated in ICM but remains unchanged in HCM." (PMID 40849623, 2025).
ischemic heart disease (1 paper, 2025). "By elucidating its impact on mitochondrial function, ion homeostasis, cardiomyocyte contractility, and cell survival, we advance the understanding of Letm1’s possible contribution to ischemic heart disease, laying the foundation for future therapeutic strategies." (PMID 40849623, 2025).
lung diseases (1 paper, 2010). "Together, the potential importance of LETM1 as a potential tumor suppressor gene with poor prognosis of diverse oncogenic nononcogenic lung diseases have prompted us to examine the possibility that LETM1 may function to regulate mitochondria and lung tumor growth." (PMID 20824095, 2010).
papillary thyroid carcinoma (1 paper, 2019). "LETM1 is associated with mitochondrial function and PKB/Akt signaling, and LETM1 overexpression increased Akt and pAkt in human papillary thyroid carcinoma." (PMID 31500591, 2019).
renal cell carcinoma (1 paper, 2021). "Meanwhile, high expression of LETM1 in renal cell carcinoma has also been reported." (PMID 34605738, 2021).
thyroid cancer (1 paper, 2016). "Future study will be focusing on further mechanistic explanations of LETM1-PKB/AKT-YAP1-PDGF signal pathway to develop new druggable targets for invasive or metastatic thyroid cancers." (PMID 27556512, 2016). "In clinical data analysis, LETM1 up-regulation in thyroid cancer was found to be related to aggressive tumor features such as lymphovascular invasion (LVI, P < 0.001) and lymph node metastasis (LNM, P = 0.011)." (PMID 27556512, 2016). "Collectively, these data suggest that up-regulation of LETM1 induces sustained activation of proliferative signaling pathways, such as PDGF signal pathway by AKT induced YAP1 transactivation, resulting in aggressive thyroid cancer phenotypes." (PMID 27556512, 2016).
cancer (22 papers, 2010 to 2025). A tumor composed of atypical neoplastic, often pleomorphic cells that invade other tissues. "LETM1 appears to be increased in several cancer subtypes and is linked to cancer stem cell‐like populations." (PMID 40985275, 2025). "LETM1 is associated with poor prognosis in various malignant tumors, whereas the biological role and mechanism of action of LETM2 in cancer remain poorly understood." (PMID 38654380, 2024). "Our results confirmed the findings of Piao21 and showed that LETM1 is an important factor associated with cancer stemness in CRC." (PMID 33314691, 2021). "Because autophagy is often associated with cancer cell growth and death, we tested the effects of LETM1 on autophagy in CRC cells." (PMID 33314691, 2021). "LETM1 is highly expressed in many different types of tumours, especially in cancer stem cells, and is associated with poor prognosis." (PMID 35582450, 2020). "There is accumulating evidence that LETM1 expression is significantly increased in several kinds of cancers and is associated with poor prognosis." (PMID 33552978, 2020). "Taken together, our studies strongly indicate that the expression of LETM1 is positively associated with cancer stemness-related gene expression in NSCLC." (PMID 31500591, 2019). "Recent findings have shown that LETM1 regulates mitochondrial biogenesis and translation system which can be implicated in tumorigenesis and cancer." (PMID 20824095, 2010). "Moreover, the TMEM33 expression level was remarkably positively correlated with similar genes of RNF4, OCIAD1, TMED5, DHX15, MED28 and LETM1, which have been reported to be implicated in tumorigenesis of various cancers." (PMID 35832191, 2022). "Moreover, LETM1 is highly expressed in many human malignant tumours and is closely associated with lymph node metastasis, disease‐free survival and overall survival rates." (PMID 33314691, 2021). "Recent reports suggest that LETM1 is associated with cancer stem cell–like properties." (PMID 33314691, 2021). "How do point mutations in LETM1 associated with cancer affect the structure and function of LETM1?" (PMID 30642051, 2019). "Taken together, these results indicate that LETM1 may be an important factor associated with cancer stemness." (PMID 31500591, 2019). "Mitochondrial Ca2+ efflux through reported ion exchangers such as NCLX, LETM1, and GHITM has also been implicated in metabolic and cancer phenotypes." (PMID 40985275, 2025). "Accordingly, we next examined the regulatory impact of LETM1 on cancer stemness characteristics in CRC cells." (PMID 33314691, 2021). "Previous studies have shown that high LETM1 level is closely related to cancer stemness proteins in CRC." (PMID 33314691, 2021). "Interfering with LETM1 downregulated related proteins and significantly reduced cancer cell proliferation, migration and invasion via a downstream control of Wnt/β-Catenin signaling pathway." (PMID 34605738, 2021). "The open questions surrounding the substrate specificity and stoichiometry of LETM1 (Section 2.2) preclude understanding of roles of LETM1 mediated transport in cancer." (PMID 34069047, 2021). "As a mitochondrial inner membrane protein, LETM1 has been a potential target marker for a variety of cancer studies." (PMID 34605738, 2021). "Accordingly, LETM1-KD reduced the expression of cancer stemness-related genes, increased AMPK activation, arrested cell cycle, lowered the number and size of tumor spheroids, and markedly inhibited cell proliferation." (PMID 33815143, 2021). "Leucine zipper‐EF‐hand–containing transmembrane protein 1 (LETM1) is a mitochondrial inner membrane protein that is highly expressed in various cancers." (PMID 33314691, 2021). "LETM1 silencing also suppressed cancer stem cell–like properties and induced autophagy in CRC cells." (PMID 33314691, 2021).